PAX5 (paired box 5)
Diseases named in the same sentence as PAX5 in open-access papers (continued):
Sharing a sentence is not in itself a finding about the gene and the disease.
breast carcinoma (continued). "To demonstrate the clinical relevance of our findings, we investigated Pax-5 expression profiles on formalin-fixed paraffin-embedded (FFPE) tissues arrays from breast cancer patients using immunohistochemistry (IHC) staining." (PMID 28076843, 2017). "We also observed that Pax-5 inhibited and reversed breast cancer epithelial to mesenchymal phenotypic transitioning." (PMID 28076843, 2017). "Our results provide the largest compilation of Pax-5 expression profiles in mammary tissues and demonstrate that Pax-5 is almost ubiquitously expressed (97%) in all breast cancer cell lines and clinical tissues examined." (PMID 28076843, 2017). "Given the paucity of data relating to Pax-5 gene expression in breast cancer cells, we studied the roles of Pax-5 in breast cancer processes." (PMID 28076843, 2017). "We first measured cell proliferation rates in MCF7 and MB231 breast cancer cell lines in response to Pax-5 recombinant expression." (PMID 28076843, 2017). "Altogether our data suggest that Pax-5 promotes breast cancer cell adhesion and induces pro-adherent gene expression signatures." (PMID 28076843, 2017). "More interestingly, we found that Pax-5 is a key player in breast cancer cell epithelialisation through the suppression of malignant features and inhibition of EMT." (PMID 28076843, 2017). "We thus believe that further studies will better define and elucidate Pax-5-mediated pathways, and advance our discovery of more effective treatments and diagnostics strategies for breast cancer patients." (PMID 28076843, 2017). "Our results support a role for Pax-5 as a potent regulator of cell signaling events leading to the development, maintenance and progression of breast cancer disease." (PMID 28076843, 2017). "In the present study, we set out to profile Pax-5 expression in mammary tissues and elucidate the cellular and molecular roles of Pax-5 in breast cancer processes." (PMID 28076843, 2017). "We thus set out to profile Pax-5 gene expression in various mammary cancer cell lines and clinical samples." (PMID 28076843, 2017). "Although a greater number of scientific reports highlighted PAX5 as a tumor suppressor in breast cancer, in some cases it may have a dual face and act as promoter of the aggressive phenotype." (PMID 40506992, 2025). "For instance, it has been suggested that PAX5 could modulate the epithelial to mesenchymal transition (EMT) process in breast cancer cells by inducing pro-epithelial characteristics." (PMID 40506992, 2025). "Therefore, PAX5 plays a predominantly anti-proliferative role in breast cancer by modulating EMT, promoting pro-epithelial characteristics, and regulating tumor-suppressive pathways." (PMID 40506992, 2025). "Taken together, we revealed a feedback loop of PAX5 and miR-142, which could affect breast cancer progression by regulating DNMT1 and ZEB1." (PMID 37403081, 2023). "Next, we further investigated the regulation of PAX5 expression in breast cancer." (PMID 37403081, 2023). "Nevertheless, the specific regulation mechanism of PAX5 in breast cancer is still uncertain." (PMID 37403081, 2023). "Next, we further explored the regulator of PAX5 in breast cancer." (PMID 37403081, 2023). "For better acknowledgement of PAX5 expression pattern in breast cancer cell lines, western blot was performed and indicated that PAX5 was over-expressed in normal breast cell line ZR-75-1 and luminal A subtype breast cancer cell line MCF-7, while rarely expressed in other breast cancer cell lines." (PMID 37403081, 2023). "The expression of PAX5 in breast cancer was detected by qRT-PCR and western blot." (PMID 37403081, 2023). "Pax-5 inhibited the proliferation of breast cancer cells by increasing the expression of miR-215." (PMID 35682560, 2022). "Interestingly, conversely to 3′UTR splicing in B-cells, PAX5 3′UTR shortening in breast cancer cells is primarily manifested by alternative polyadenylation (APA)." (PMID 36077495, 2022).
breast carcinoma (continued). "In opposition, numerous studies functionally characterize PAX5 as a tumor suppressor in hepatocellular carcinoma, breast carcinoma, esophageal squamous cell carcinoma, retinoblastoma, gastric cancer, Merkel cell carcinoma, ovarian cancer, and head and neck squamous cell carcinoma." (PMID 36077495, 2022). "Additionally, Kaplan-Meier plot showed breast cancer patients with lower PAX5 expression live shorter than those with higher, while the survival rate of patients with higher PAX6 expression decreased compared to those with lower expression." (PMID 32693820, 2020). "In general, we observe that Pax-5 has an anti-tumorigenic role in breast cancer cells." (PMID 28076843, 2017). "Mechanistically, we observed that Pax-5 inhibits ERK activation pathways which may support Pax-5-induced attenuation of breast cancer growth." (PMID 28076843, 2017). "We also elucidate the molecular and cellular roles of Pax-5 in breast cancer processes." (PMID 28076843, 2017). "In contrast to B-cell cancer lesions, the specific expression signatures and roles of Pax-5 in breast cancer progression are relatively unknown." (PMID 28076843, 2017). "Given that E-cadherin is a potent inhibitor of EMT, we set out to examine whether Pax-5 could mitigate transiently-induced EMT in breast cancer cells." (PMID 28076843, 2017). "Interestingly, our studies reveal that Pax-5 inhibits aggressive features and confers anti-proliferative effects in breast carcinoma cells in contrast to its oncogenic properties in B cell cancers." (PMID 28076843, 2017). "We next evaluated breast cancer invasion and its modulation by Pax-5." (PMID 28076843, 2017). "Recently, we and others have suggested a role for Pax-5 in phenotypic transitioning programs (EMT-MET) which in turn could modulate breast cancer aggressivity and disease progression." (PMID 28076843, 2017). "Given the epithelial-like characteristics induced by Pax-5 in breast cancer cells, we wanted to assess the effects of Pax-5 on cancer cell malignancy in terms of aggressive cancer cell processes (i.e. migration, invasion, anchorage-independent growth, and spheroid formation in 3D cultures)." (PMID 28076843, 2017). "Although controversial, Pax-5 expression has also been detected in breast carcinoma." (PMID 28076843, 2017). "Our findings strongly support a beneficial role for Pax-5 expression in breast cancer tumors." (PMID 28076843, 2017). "Interestingly, PAX5 itself is reported as being frequently methylated in breast cancer and its overexpression in cell lines is reported to reduce the cancer phenotype by promoting normal epithelial characteristics." (PMID 25960784, 2015). "Indeed, PAX5 promotes the expression of miR-142, which could affect breast cancer progression by regulating DNMT1 and ZEB, involved in the methylation of Pax5 promoter." (PMID 40506992, 2025). "Pax-5 could inhibit the invasion and proliferation of breast cancer cells by suppressing EMT." (PMID 35682560, 2022). "However, the apparent dual role of PAX5 in breast cancer, as both a tumor suppressor and a potential promoter of aggressive phenotypes, may be attributed to the heterogeneity of breast cancer subtypes and the context-dependent nature of transcriptional regulation." (PMID 40506992, 2025). "Conditional expression of microRNA-155 in breast cancer models highlighted its suppression of IKKε (IKBKE) expression, followed by down-regulation of NF-κB signaling, a process also modulated by PAX5." (PMID 40506992, 2025). "In conclusion, TGF-β promotes the conversion of NFs into CAFs in the breast cancer TME, accompanied by an increase in PAX5 and lncRNA PRKCQ-AS1 expression." (PMID 41029829, 2025). "In summary, we exhibited a feedback regulation loop formed by PAX5, miR-142, and DNMT1/ZEB1, which play crucial roles in breast cancer development." (PMID 37403081, 2023).
breast carcinoma (continued). "For example, Pax-5 promoted an oncogenic role in specific lymphoproliferative cancers (ex: CLL and DLBCL), whereas in mammary cancers, Pax-5 elicited tumor suppressor features and promoted cellular epithelialization." (PMID 35011638, 2021). "As a whole, our date revealed that the orthologous intron regions of PAX5 and PAX6 binding motifs between human and dog have similar CG methylation alterations in breast cancers." (PMID 32693820, 2020). "Briefly, in this part of the study, we found that there was a requirement for new methylated genes other than PAX5 and TMPRSS2 to measure the effects of methylation inhibitor in breast cancer tissue in in vitro models." (PMID 30792990, 2019). "In a previous study PAX5, TMPRSS2, and SBDS genes that we are investigating were reported to be methylated more than 60% in breast cancer and malignant melanoma cell lines." (PMID 30792990, 2019). "To confirm Pax-5 expression from FFPE samples, we extracted total RNA from two FFPE breast cancer tissue samples (BCT-1 and BCT-2) and performed RT-qPCR to detect Pax-5 mRNA." (PMID 28076843, 2017). "The most frequently hypermethylated genes (MSH6, CDH13, PAX5, PAX6 and WT1) were similar for male and female breast cancer." (PMID 22765268, 2012). "Methylation is involved in the development of female breast cancer, with frequent methylation of PAX6, BRCA2, PAX5, WT1, CDH13 and MSH6 in ductal carcinoma in situ and invasive ductal cancer." (PMID 22765268, 2012). "On the other hand, the high frequency of methylation in MSH6, PAX5, PAX6 and CDH13 was shared between male and female breast cancer." (PMID 22765268, 2012). "In summary, PAX5-miR-142-DNMT1/ZEB1 constructed a negative feedback loop to regulate the progression of breast cancer, which provided emerging strategies for breast cancer therapy." (PMID 37403081, 2023). "Interestingly, a recent study using canine mammary tumours as a model for human breast cancer, identified hypermethylation in the third intron of LRIG1 overlapping with a tumour suppressive PAX5 DNA binding motif." (PMID 35440669, 2022). "To date, the functional role of PAX5 expression and function in non-hematopoietic cancers has largely been elucidated in breast cancer models." (PMID 36077495, 2022). "Thus, CD81 and Pax5-induced CD81 appeared to function as a positive regulator of cell motility, which is in agreement with previous reports using dendritic, breast cancer, and B cells." (PMID 34824296, 2021). "Interestingly, genes with frequent methylation in male breast cancer (MSH6, CDH13, PAX5, PAX6 and WT1) were also very commonly methylated in female breast cancer." (PMID 22765268, 2012). "Thus, we predicted the existence of CpG island of PAX5 promoter by Meth primer, and detected the methylation status of PAX5 in four subtypes of breast cells by BSP sequencing, which results showed the abnormal methylation of PAX5 in breast cancer." (PMID 37403081, 2023). "However, PAX5 expression during the shifts of phenotypic programs (EMT and MET) necessary for successful metastasis may also produce dichotomous outcomes for breast cancer disease." (PMID 36077495, 2022). "However, the role of Pax-5 in epithelial cell identity and EMT-MET processes may present dichotomous outcomes for breast cancer patients." (PMID 28076843, 2017). "To expose some molecular mechanisms by which Pax-5 could suppress breast cancer aggressive features, we performed RT-qPCR on molecular mediators of breast cancer malignancy such as: MMP2 and MMP9; vimentin and fibronectin following Pax-5 transfection of MB231 cells." (PMID 28076843, 2017). "In fact, PAX5 hypermethylation has been described in many non-hematological cancers, particularly where PAX5 is characterized as a tumor suppressor (e.g., hepatocellular carcinoma, ovarian carcinoma; head and neck cancer, gastric cancer, lung and breast cancer malignancies)." (PMID 36077495, 2022).
breast carcinoma (continued). "It was shown that PAX5 and TMPRSS2 were not suitable genes to measure the effects of methylation inhibitors in breast cancer tissue." (PMID 30792990, 2019). "However, the methylation status of selected PAX5, TMPRSS2, and SBDS genes was examined in cell lines but not primary tumor tissue of patients with breast cancer and malignant melanoma in the literature." (PMID 30792990, 2019).
Hodgkins lymphoma (15 papers, 2008 to 2025). A heterogeneous group of malignant lymphoid neoplasms of B-cell origin characterized histologically by the presence of Hodgkin and Reed-Sternberg (HRS) cells in the vast majority of cases. "One cHL with nodular sclerosis subtype is described to be of rare T-cell differentiation, identified by missing expression of the transcription factor PAX-5 and positive staining for granzyme B in the H-RS cells." (PMID 39001514, 2024). "Immunohistochemistry of the biopsy contributed to the diagnosis of Stage IVb classical Hodgkin’s lymphoma, being positive for markers CD15 and CD30, and weakly positive for CD20, paired box protein 5 (PAX5), and programmed death-ligand 1 (PD-L1)." (PMID 41170247, 2025). "Usually, NOTCH1 is repressed by PAX5; however, aberrant expression of NOTCH1 interferes with the B lymphoid phenotype of neoplastic B cells in the classical Hodgkin lymphoma." (PMID 32604737, 2020). "PAX5 expression is absent in anaplastic large cell lymphomas, therefore PAX5 positivity in Hodgkin lymphoma cells can be used to differentiate Hodgkin’s lymphoma from anaplastic large cell lymphoma." (PMID 40506992, 2025). "In the three different kinds of B lymphocytes in Hodgkin’s lymphoma and Burkitt’s lymphoma (Raji, Namalwa and L428 cells) (PRJNA190710), compared to that in cells in the control group, the binding regions of PAX5 in LTB showed higher binding strength (input samples)." (PMID 33397394, 2021). "Classic Hodgkin lymphoma was ruled out based on the diffuse expression of the T-cell markers CD2, CD3, and CD8, as well as a complete lack of PAX5 expression." (PMID 38921179, 2024). "Moreover, unlike classic Hodgkin lymphoma, primary cutaneous ALCL rarely expresses PAX5 and is negative for EBV (which may be positive or negative in classic Hodgkin lymphoma)." (PMID 37627126, 2023).
Burkitt lymphoma (12 papers, 2011 to 2025). A rare form of malignant mature B-cell non-Hodgkin lymphoma. "In our study, we constructed a new cell model of PAX5+/− using gene editing technology which knocked out one PAX5 allele in Raji cell line (lymphoblastoid cell line derived from Burkitt lymphoma)." (PMID 28316978, 2017). "In addition to B-ALL, PAX5 mutations and rearrangements (such as PAX5 t (p13;q32)) were identified in Burkitt’s lymphoma, follicular lymphoma as well as diffuse large B cell lymphoma (DLBCL)." (PMID 38318177, 2024). "Burkitt Lymphoma stained positive for PAX5 in four (66%), c-Myc in three (50%), and EBV in two (33.3%) cases." (PMID 41426849, 2025). "Moreover, inducing the expression of the I107R mutant with Dox in Burkitt lymphoma Namalwa cells resulted in impaired cell proliferation and the repression of Pax5, CIITA, and ID3." (PMID 28842558, 2017). "B-cell markers, including CD22, CD19, CD79a, CD20, Pax5, and germinal center markers, such as CD10 and BCL-6, are expressed in Burkitt lymphoma." (PMID 40115528, 2025). "Burkitt lymphoma has a germinal center B-cell (GCB) immunophenotype and is positive for the pan-B-cell antigens CD20, CD79a, and PAX5, and germinal center antigens CD10 and Bcl6." (PMID 26416427, 2015). "MYC rearrangements in DLBCL can be partnered with IGH but, compared with Burkitt lymphoma, are more frequently partnered with the IGL or to non-IG genes such as BCL6, BCL11A, PAX5 or ICAROS49." (PMID 26416427, 2015). "Immunohistochemical and molecular studies demonstrated typical features of sporadic Burkitt lymphoma: the atypical cells were positive for CD20, CD79a, CD10, CD23, HLA-DR, bcl-6, PAX5, c-myc, and cytoplasmic IgM, but negative for CD3, CD5, CD15, CD30, CD34, TdT, bcl-2, and MUM1." (PMID 34868769, 2021). "In contrast to Burkitt lymphoma (BL), where MYC is almost exclusively fused to an immunoglobulin locus, up to 50% of MYC translocations in DLBCL involve non-immunoglobulin genes, including among others BCL6, PAX5, and IKZF1." (PMID 35060000, 2022).
hepatocellular carcinoma (12 papers, 2014 to 2026). A malignant tumor that arises from hepatocytes. "It’s well reported that PAX5 promoter is hypermethylated in various cancer types, including hepatocellular carcinoma, gastric cancer and esophageal cancer, resulted in the down-regulated expression of PAX5." (PMID 34823564, 2021). "In hepatocellular carcinoma cells, expression of the proteins Paired Box 5 (PAX5) and Zinc Finger Protein 5 Homolog (ZFP5) positively correlate with FHL2 expression, while potential binding sites for these proteins were found in the FHL2 promoter sequence." (PMID 34685595, 2021). "Besides, a significantly higher methylation of PAX5 was also detected in hepatocellular carcinoma (HCC)." (PMID 37403081, 2023).
lung carcinoma (9 papers, 2010 to 2021). "The expression of PAX5 and PAX8 are different in lung cancer tissues in order to further identify potential therapeutic targets, while PAX5 inclined to expressed in SCLC cells, overexpression of PAX8 in most NSCLC cell lines." (PMID 29997452, 2018). "Ectopic expression of PAX5 in silenced lung cancer cell lines (A549 and H1975) inhibited their colony formation and cell viability, arrested cell cycle at G2 phase and suppressed cell migration/invasion as well as tumorigenicity in nude mice." (PMID 26843424, 2016). "In the present study, we found lung cancer specific hypermethylation of PAX5 and MEIS2." (PMID 28634396, 2017). "However, we have previously shown that PAX5 and PAX8 are differentially expressed in lung cancers; while PAX5 expression is restricted to SCLC cells, PAX8 expression is apparent more in NSCLC cell lines." (PMID 24628993, 2014). "Promoter methylation of eight lung cancer-specific genes (CDO1, TAC1, SOX17, HOXA7, HOXA9, GATA4, GATA5, and PAX5) was detected using nanoparticle-based DNA extraction (MOB) followed by qMSP." (PMID 32138766, 2020). "However, the role of PAX5 in non‐small cell lung cancer (NSCLC) pathogenesis remains unclear." (PMID 26843424, 2016). "We have previously shown differential expression of PAX5 and PAX8 in lung cancer." (PMID 24628993, 2014). "Interestingly, the majority of breast samples tested positive (97%) for Pax-5 protein expression when compared to control samples consisting of positive (B cells from tonsil sections) and negative (lung cancer sections)." (PMID 28076843, 2017).